ACTN3 (actinin alpha 3)
Diseases named in the same sentence as ACTN3 in open-access papers (continued):
Sharing a sentence is not in itself a finding about the gene and the disease.
chronic heart failure (3 papers, 2014 to 2025). "R577X polymorphism in the ACTN3 gene was independently associated with worse survival in patients with chronic heart failure." (PMID 25059829, 2014). "Interestingly, carriers of the ACTN3 X allele have a 1.72-fold higher risk of death than those with the ACTN3 577RR genotype in patients with congestive heart failure, suggesting that the ACTN3 genotype may be a prognostic marker for this condition." (PMID 40150043, 2025).
diabetes (3 papers, 2011 to 2023). "An influence of this R577X polymorphism in ACTN3 has been suggested, with changes in the energetic metabolism, which could be potentially involved with diabetes development." (PMID 37948561, 2023). "Both ACTN3 R577X and PON1 T(-107)C polymorphisms are associated with nutritional status and blood glucose and lipid levels in women with diabetes/hypertense." (PMID 37948561, 2023). "As insulin resistance is a known predictor of diabetes, the role of ACTN3 expression deserves further investigation." (PMID 21299892, 2011).
heart failure (3 papers, 2014 to 2020). Inability of the heart to pump blood at an adequate rate to meet tissue metabolic requirements. "Our findings suggest that heart failure patients carrying X allele of the ACTN3 R577X polymorphism had significantly shorter survival time compared with patients with the RR genotype and the presence of the X allele conferred a worse prognosis." (PMID 25059829, 2014). "This is the first study to investigate the possible association of the ACTN3 gene with the prognosis of heart failure." (PMID 25059829, 2014). "Our study suggested that R577X polymorphism in the ACTN3 gene modulates survival and could be used, in the future, as a prognostic marker in heart failure." (PMID 25059829, 2014). "In this scenario, the main aim of this study was to assess whether ACTN3 R577X polymorphism is associated with mortality in heart failure patients." (PMID 25059829, 2014). "While the relationship between metabolome and ACTN3 genotype needs to be explored in a larger cohort including clinical populations (i.e heart failure, COPD) ours is the first to report metabolite differences in humans related the ACTN3 genotype." (PMID 26107372, 2015). "We also did not detect Actn3 in the myocardium of patients with heart failure by confocal microscopy (not shown)." (PMID 32774516, 2020).
Insulin resistance (3 papers, 2011 to 2020). Increased resistance towards insulin, that is, diminished effectiveness of insulin in reducing blood glucose levels. "Some bimodally expressed genes had modest associations with pre-diabetic phenotypes, of note ACTN3 with insulin resistance." (PMID 21299892, 2011). "We observed a likely association of insulin sensitivity with mode of ACTN3 expression, with 42.2% of the individuals falling in the higher expressed mode which was associated with insulin resistance." (PMID 21299892, 2011). "On the other hand, other studies showed that carriers of the ACE D polymorphism had a higher risk of myocardial infarction, and the ACTN3 X allele was associated with a higher risk of developing insulin resistance, which is a known factor of increased mortality." (PMID 32872456, 2020).
Pompe disease (3 papers, 2014 to 2021). "We demonstrate that ACE and ACTN3 polymorphisms are genetic factors able to modulate the clinical phenotype of patients affected with Pompe disease." (PMID 25103075, 2014). "Similar to other lysosomal storage disorders, genetic, epigenetic, and environmental factor including race, ethnicity, gender, and polymorphisms in other genes (angiotensin-converting enzyme (ACE), alpha-actinin-3 (ACTN3)) have been suggested to affect the onset and progression of Pompe disease." (PMID 32932790, 2020). "While the pro-fibrotic polymorphism in LTBP4 found in the DBA2/J background has not been implicated in Pompe disease, polymorphisms in angiotensin-converting enzyme (ACE) and alpha-actinin 3 (ACTN3) impact disease onset within LOPD." (PMID 34778273, 2021).
bruxism (2 papers, 2024 to 2025). Excessive clenching of the jaw and grinding of the teeth. "Variations in genes like 5HTR2A, DRD2, DRD3, ANKK1, COMT, MMP9, ACTN3, and ANKK1 are linked with the susceptibility to Bruxism." (PMID 40291793, 2025). "What is more, associations of bruxism and metalloproteinase 9 (MMP9) and cathecol-o-methyltransferase (COMT) genes in adults and alpha-actinin-3 (ACTN3) gene in children were also reported." (PMID 39685550, 2024).
cardiomyopathies (2 papers, 2024 to 2025). "The review identified key gene variants affecting athletic performance: endurance (AMPD1, PPARGC1A), power (ACTN3, NOS3), strength (PPARG), and injury susceptibility (COL5A1, MMP3), while also examining inherited conditions like cardiomyopathies (MYH7, MYBPC3)." (PMID 40724525, 2025).
COVID-19 (2 papers, 2024 to 2025). A disease caused by infection with severe acute respiratory syndrome coronavirus 2. "The effects of ACE1 rs4646994, PPARGC1A rs8192678, and ACTN3 rs1815739 polymorphisms on COVID-19 severity were evaluated." (PMID 40150043, 2025). "Some studies suggest that ACTN3 polymorphisms may influence the inflammatory response, which plays a critical role in determining COVID-19 severity." (PMID 40150043, 2025). "Based on this background, the present study is set to investigate the roles of the ACE rs4646994, ACTN3 rs1815739, and PPARGC1A rs8192678 polymorphisms in determining the severity of COVID-19 outcomes." (PMID 40150043, 2025). "In terms of combined genetic effects, polymorphisms in ACE, ACTN3, and PPARGC1A likely interact to influence COVID-19 outcomes." (PMID 40150043, 2025). "Since fast-twitch fibers are also present in respiratory muscles, variations in ACTN3 could affect the strength and endurance of these muscles, potentially influencing respiratory efficiency and contributing to the severity of COVID-19." (PMID 40150043, 2025).
malocclusion (2 papers, 2023 to 2025). "Candidate genes such as COL1A2, matrix metalloproteinases (MMP-1, MMP-9), and muscle-related genes (ACTN2, ACTN3) have been implicated in craniofacial morphology and malocclusion risk." (PMID 41153339, 2025).
prostate carcinoma (2 papers, 2019 to 2025). A carcinoma that arises from epithelial cells of the prostate gland. "Maybe most interestingly in regard to our data on promotion of prostate cancer cell motility by PIM1 and NFATC1, there were several genes encoding regulators of the cytoskeletal actin network (INF2, FHOD1, ACTN3, CORO1B) and cell adhesion (COL6A2, PXN, ITGA5)." (PMID 31730483, 2019). "Furthermore, our results suggest that ACTN3 R577X genotype will contribute to the clinical variability in patients with partial or mild androgen insensitivity syndrome and may also affect the health outcomes and treatment response of patients with prostate cancer who undergo ADTs." (PMID 40864710, 2025).
rhabdomyolysis (2 papers, 2019 to 2022). Necrosis or disintegration of skeletal muscle often followed by myoglobinuria. "Studies have shown that although the ACTN3 R577X mutation does not cause a disease, it is closely related to exercise-induced rhabdomyolysis, increasing the possibility of exertional rhabdomyolysis." (PMID 35313994, 2022).
type 2 diabetes (2 papers, 2014 to 2018). "Given that higher levels of muscle mass are associated with better insulin sensitivity, and that ACTN3 genotype can modify muscle cross sectional area and fiber type, there is the potential that ACTN3 genotype may impact type-II diabetes risk, either directly or indirectly." (PMID 29416549, 2018). "Similarly, there is an unclear relationship between ACTN3 genotype and metabolic health; one study indicates that the XX genotype is present with an increased frequency in type-II diabetes patients, but clearly further research is required to better understand this relationship." (PMID 29416549, 2018).
arrhythmogenic right ventricular cardiomyopathy (1 paper, 2024). "Moreover, we found that the expressions of ACTN3, cacna2d1, and TGA2, all associated with arrhythmogenic right ventricular cardiomyopathy, were considerably altered, which explains cardiac defects in some patients." (PMID 39619318, 2024).
Atrophy (1 paper, 2021). Any weakening or degeneration, especially through lack of use. "The decrease in Mib1 or accumulation of Actn3 in skeletal muscle with age represents as a therapeutic target to treat or ameliorate age-associated muscle atrophy." (PMID 33637766, 2021).
Desminopathy (1 paper, 2024). "In agreement with the ATPase staining results, the type 2 fiber-associated proteins alpha-actin-3 (ACTN3) and troponin C (TNNC) are among the most downregulated DAPs in desminopathy compared to titinopathy." (PMID 39239540, 2024).
diabetic neuropathy (1 paper, 2022). A chronic, pathological complication associated with diabetes mellitus, where nerve damages are incurred due to diabetic microvascular injury involving small blood vessels that supply these nerves, resulting in peripheral and/or autonomic nerve dysfunction. "In line with our peak-CIPN dataset, mRNA of the actin-binding protein Actn3 and the ATPase Atp2a1 were increased 4 weeks after induction of diabetic neuropathy in rat DRG, while contrary to our findings, the expression of the myosins Mylpf and Mhy1 was decreased." (PMID 35250568, 2022).
dilated cardiomyopathy (1 paper, 2024). Cardiomyopathy which is characterized by dilation and contractile dysfunction of the left and right ventricles. "Particularly, LTBP4 and ACTN3 polymorphisms and genotypes have been proposed to be associated with a higher risk of dilated cardiomyopathy." (PMID 39342355, 2024).
Hematuria (1 paper, 2019). The presence of blood in the urine. "Further studies are needed to determine the association between hematuria and ACTN3 polymorphism due to low sample size of this study." (PMID 31244673, 2019).
idiopathic inflammatory myopathies (1 paper, 2021). "There is some evidence that ACTN3 genotype might alter the susceptibility to—and progression of—muscle disease, with the X-allele increasing the risk of developing idiopathic inflammatory myopathies." (PMID 34069995, 2021).
iron deficiency (1 paper, 2019). "We show in our preliminary results that marathoners with the ACTN3 XX genotype have reduced susceptibility to hematuria and iron deficiency." (PMID 31244673, 2019).
left ventricular dilation (1 paper, 2024). "The left ventricular dilation-free survival rate was different between patients with the RR, RX, and XX genotypes (p = 0.023) and lower in patients with the ACTN3 null genotype compared with the ACTN3 positive genotype (HR: 9.04, 95% CI = 1.77 to 46.20, p < 0.05)." (PMID 39342355, 2024).
McArdle) disease (1 paper, 2011). "In humans, the metabolic effects of ACTN3 genotype may act as a modifier of disease severity: the X allele has recently been shown to benefit exercise capacity phenotypes (i.e. aerobic capacity) in women with muscle (McArdle) disease." (PMID 21407828, 2011).
muscle atrophy (1 paper, 2021). The loss of muscle tissue due to inactivity or disease. "Thus, our findings on Mib1-dependent accumulation of Actn3 with age will expand the understanding of how age-associated regulation of sarcomeric proteins is implicated in age-associated muscle atrophy." (PMID 33637766, 2021).
muscle hypertrophy (1 paper, 2024). "Finally, athletes with the RR genotype have higher levels of testosterone, which may explain, in part, the association between the ACTN3 RR genotype, skeletal muscle hypertrophy and power athlete status, as athletes carrying the RR genotype are more likely to be power athletes." (PMID 38609671, 2024).
muscular dystrophy (1 paper, 2025). Muscular dystrophy (MD) refers to a group of more than 30 genetic diseases characterized by progressive weakness and degeneration of the skeletal muscles that control movement. "Up-regulation of this pathway in Actn3 KO mice also enhances the response to exercise training, modifies the muscle adaptive response to denervation and immobilization, and slows the progression of muscular dystrophy in mdx mice." (PMID 40864710, 2025).
renal failure (1 paper, 2026). "The ACTN3 X allele is associated with earlier onset of renal failure and increased susceptibility to tubulointerstitial disease." (PMID 41677364, 2026).
Stroke (1 paper, 2025). Sudden impairment of blood flow to a part of the brain due to occlusion or rupture of an artery to the brain. "In the current study, Actn2 expression was upregulated on the 3rd day after stroke, while Actn3 was downregulated." (PMID 41226396, 2025).
viral infections (1 paper, 2018). "The existence of geo-epidemiological precedents in various immune-related disorders, viral infections, and the adaptive evolution of ACTN3 indirectly support a latitudinal factor to IS incidence although only additional epidemiological studies on this topic may be conclusive." (PMID 30486850, 2018).
cancer (5 papers, 2022). A tumor composed of atypical neoplastic, often pleomorphic cells that invade other tissues. "The search for the upregulated genes in three types of CSCs revealed Actn3, Ccnd2, Col4a1, and Col4a2, which have been linked to tumor aggressiveness, poor prognosis, cancer cell proliferation, and cell migration." (PMID 35063003, 2022). "Finally, the role of actinin alpha 3 (ACTN3), a protein involved in crosslinking actin-containing thin filaments, has not been studied in cancer." (PMID 35008958, 2022).
tumor (4 papers, 2022 to 2023). "An enrichment analysis with Toppgene revealed that over 10 of the 17 significantly upregulated genes in the tumours of the female mice were skeletal muscle genes such as Acta1, Actn3, Myh2, Myh4 and Des." (PMID 37840045, 2023).
infection (3 papers, 2016 to 2025). The state of being infected such as from the introduction of a foreign agent such as serum, vaccine, antigenic substance or organism. "This cluster contained Acta1, encoding smooth muscle actin, as well as the actin crosslinking protein gene Actn3 and two myosin genes (Myo1h and Myh2), suggesting that both infection and Muc1 knockout disrupt the cytoskeleton." (PMID 32793510, 2020).
cardiovascular disease (1 paper, 2015). "Taken together, these associations suggest that prospective and retrospective ACTN3 genotyping may provide novel insights into human athletic performance and cardiovascular disease risk stratification." (PMID 26107372, 2015).
metabolic disease (1 paper, 2018). A congenital disorder (due to inherited enzyme abnormality) or acquired (due to failure of a metabolically important organ) disorder resulting from an abnormal metabolic process. "In this mini-review, we focus on the impact of a single nucleotide polymorphism in ACTN3, shown to impact muscle phenotype in elite athletes, on loss of muscle function, maintenance of bone mineral density, and metabolic disorder risk in an elderly population." (PMID 29416549, 2018).
renal disorders (1 paper, 2015). "Missense mutations in ACTN1, ACTN2 and ACTN4 cause dominantly inherited platelet, cardiac and renal disorders respectively, while a nonsense mutation in ACTN3 seems to have been beneficial during the recent evolution of some human populations." (PMID 26312134, 2015).
ACTN3 also shares sentences with these, for which no sentence is quoted: Duchenne muscular dystrophy (2 papers); dyslipidemia (2); acute myeloid leukemia (1); Alzheimer disease (1); androgen insensitivity syndrome (1); asthma (1); atopic asthma (1); chronic obstructive pulmonary disease (1); end-stage renal disease (1); hypogonadal (1); idiopathic pulmonary fibrosis (1); leiomyosarcoma (1); lysosomal storage disorders (1); malnutrition (1); Mitochondrial myopathy (1); myocardial infarction (1); myopathies (1); osteoporosis (1); ovarian carcinoma (1); prediabetes (1); protein deficiency (1); renal fibrosis (1); respiratory infections (1); Sepsis (1); Spondyloarthropathies (1).